ENSG00000291149 (novel transcript)
Synonyms: LOC154761
Gene: Long non-coding RNA gene on chromosome 7 (143,721,659 to 143,837,377, reverse strand). Ensembl gene ENSG00000291149.
Diseases named in the same sentence as ENSG00000291149 in open-access papers:
ENSG00000291149 is named in the same sentence as 2 diseases in open-access papers, as found by Europe PMC text mining. Sharing a sentence is not in itself a finding about the gene and the disease.
ENSG00000291149 shares sentences with these, for which no sentence is quoted: cancer (1 paper); glioma (1).